BMP3 (bone morphogenetic protein 3)
Diseases named in the same sentence as BMP3 in open-access papers (continued):
Sharing a sentence is not in itself a finding about the gene and the disease.
BMP3 also shares sentences with these, for which no sentence is quoted: bladder cancer (3 papers); rheumatoid arthritis (3); cholangiocarcinoma (2); Osteopenia (2); adenocarcinoma (1); atherosclerosis (1); brain cancer (1); breast tumours (1); calcification (1); chondrodysplasia (1); chronic renal diseases (1); colorectal adenoma (1); diabetic retinopathy (1); esophageal squamous cell carcinoma (1); essential hypertension (1); Hyperkeratosis (1); Intellectual disability (1); lung adenocarcinoma (1); Multiple myeloma (1); ocular coloboma (1); osteomyelitis (1); periodontitis (1); retinal detachment (1); retinal disorder (1); small cell lung carcinoma (1); vitamin D deficiency (1).